CD4 (CD4 molecule)
Diseases named in the same sentence as CD4 in open-access papers (continued):
Sharing a sentence is not in itself a finding about the gene and the disease.
infection (continued). "Adding coreceptor signaling could function by stabilizing the transiently activated conformation (analogous to CD4/coreceptor stabilization of Env in State 3), allowing more time for Trx1 to approach in native infection, perhaps compensated for in our assays with sufficient Trx1 concentration." (PMID 39912667, 2025). "Therefore, increasing CD4+ T cell levels in severe neurosurgical patients may enhance the anti-infection ability of patients and improve the prognosis." (PMID 39792837, 2025). "Similarly, Tat-LNP X was able to induce productive infection in primary CD4+ T cells infected with an HIV reporter virus (pMorpheus-V535; p = 0.0025) similar to levels seen after T cell activation with the mitogens phorbol 12-myristate 13-acetate (PMA) and ionomycin." (PMID 40442114, 2025). "After infection with Eimeria tenella coccidia in chickens, the effect of the drug on T cell activation in the broiler intestine was evaluated by flow cytometry to detect the expression of CD4+ and CD8+ in lymphocytes CD3+ in the peripheral blood on the 7th and 10th day in each group." (PMID 41475173, 2025). "Interestingly, the differences in the balance between STAT1 and STAT3 involvement were also apparent ex vivo as we observed an age-dependent gradual decline in the ratio of STAT1/STAT3 transcription for infection-induced (expanded) CD4+ T cells as well as B cell populations." (PMID 40834853, 2025). "Immunonutrition was associated with increased CD4+ and CD8+ T cell counts, reduced infection rates, and shorter hospital stays, suggesting that immunonutrition may enhance immune response and clinical outcomes, supporting its integration into comprehensive cancer care." (PMID 41256317, 2025). "They note that lack of CD4+ T cell response in the patients with HPV 18 infection may have been caused by successful immune suppression by the infection." (PMID 40589751, 2025). "Furthermore, intravenous administration of inactivated E. faecium + inactivated H1N1 virus was associated with a greater number of B cells, CD4+ T cells, and CD8+ T cells at 5 days post-infection (dpi) compared to intramuscular injection, suggesting enhanced adaptive immunity." (PMID 40909923, 2025). "The extent of immune damage (CD4 depletion) during untreated infection could also affect residual HIV infection and transcription at later times on ART, although it is also possible that this correlation is driven by an association between the HIV levels at T2 and T3 and those at T1." (PMID 39907283, 2025). "This was also reflected by the finding that CD4+ T cell recruitment to the brains of Rag1–/– animals progressively decreased when adoptive transfer was delayed, with the most dramatic impairments observed at day 7 after infection, again aligning with the onset of biofilm development." (PMID 39989461, 2025). "Although RorcΔ369 mice exhibited defects in total ILC3s, IL-17-producing, and IL-22-producing ILC3s in the colon after infection, IL-17-producing CD4+ T cells were significantly increased in RorcΔ369 mice, which may compensate for host defense against C. rodentium in RorcΔ369 mice." (PMID 40766221, 2025). "Interestingly, adoptive transfer of nonskewed bulk CD4+ or Th0 T cells were also protective in Rag1–/– mice, and both acquired a robust IFN-γ signature in the brain, suggesting that CD4+ T cell populations can be shaped by the infection milieu to provide benefit." (PMID 39989461, 2025). "Collectively, CD4+ T cells appear to play a central role in HPV clearance and the impairment of their activity by immunosuppressive strategies of HPV immune evasion or by other infections such as HIV increases the risk of persistent HPV infection and progression to disease." (PMID 40589751, 2025).
infection (continued). "Although further study is required, it is tempting to speculate that elevated IL-7 levels in infancy or later childhood may have contributed to the relatively high frequencies of both infection and clonal expansion reported for naive CD4+ T cells of participant 1001." (PMID 40048262, 2025). "Hence, this study highlights the localization and differentiation of latent-antigen-specific CD4+ T cells during primary KSHV-infection of B cells in humanized mice, and points to more efficient MHC class II presentation of viral antigens to CD4+ T cells in vivo than by infected B cells in vitro." (PMID 41350288, 2025). "However, the mechanisms by which DNA methylation regulates macrophage and CD4+ T cell responses during the progression of infection in mouse models remain unclear." (PMID 40170749, 2025). "Finally, they also described lower expression of the viral coreceptor CCR5 in the CD4+ Tcm compartment, probably contributing to the lower observed rates of infection in Tscm and Tcm, two subsets with a high proliferative capacity to replenish and maintain the CD4+ T cell compartment." (PMID 39842407, 2025). "Additionally, we studied the proportion of recent infections that, showing a low-level CD4 count, would be erroneously classified as a late diagnosis (i.e., HIV infections at a very late stage) in order to weigh the overestimation of late HIV diagnoses in Italian HIV surveillance data." (PMID 41011735, 2025). "Similarly, the lack of monocytes in CCR2-deficient mice did not significantly impact CD4+ T cell polarization post-infection." (PMID 40169810, 2025). "Acute HIV infection also induces production of chemokines (CCL2, CCL3, CCL4, and CCL5), which may recruit uninfected monocytes/macrophages and/or CD4+ T lymphocytes to the sites of virus replication, thus promoting the spread of infection and/or the establishment of virus reservoirs." (PMID 40507836, 2025). "Early infection was associated with higher CD4 counts but not with lower viral loads." (PMID 41229481, 2025). "In addition to the systemic inflammation observed during infection, the presence of marked inflammatory infiltrate in the lung environment was evidenced by the higher number of leukocytes, especially CD4+ and CD8+ T lymphocytes, in the BALF of mice infected by both strains (ME49 or CK4)." (PMID 40223760, 2025). "In addition, CD4+ T cells’ capacity to mediate protection is likely determined by the specific Mtb Ags they recognize, with each Ag exhibiting distinct expression patterns across various stages of infection." (PMID 40414893, 2025). "This suggests that effector (Tem) and regulatory (Treg) subsets of SARS-CoV-2–specific memory CD4+ T cells may differentially regulate the generation of de novo (N-specific) antibody responses in the context of breakthrough infection, but that the mechanism may be suppressed during pregnancy." (PMID 40693463, 2025). "Engagement of alloantigens with CD4 T cell TCR from the transplanted allograft or autoantigens uncovered by ischemia reperfusion injury after transplantation is a possible mechanism through which TIGIT becomes upregulated prior to exposure to infection-related antigens." (PMID 40475763, 2025). "If the host is able to mount a strong interferon-mediated response (Type I IF mediated by CD4+ T cells) at early stages of the infection, they may present with symptoms, control viral replication and limit disease severity at this stage through increased viral clearance." (PMID 40641657, 2025). "Thus, the reduced Th1 responses and expression of IFNG, TNF, GZMB, and PRF1 in CD4+ Trms may indicate the impaired anti-infection capacity in COPD airways." (PMID 40589761, 2025). "We thoroughly discuss the differences and similarities in differentiation of CD4+ TM cells under Th1, Th2, and Th17 conditions, and explore the prospects for identifying common precursors of specific CD4+ TM cells under various types of infections and exposures." (PMID 40391228, 2025).
infection (continued). "Furthermore, our findings reveal that the activation of theα4β7-Rho-GTPases-Cofilin signaling pathway by PEDV reorganizesthe actin cytoskeleton, enabling CD4+ T-cell transmigrationthrough high endothelial venules into the intestinal mucosa, resulting inthe infection of intestinal epithelial cells." (PMID 40094365, 2025). "The increased proportions of T‐cells (CD4+ central memory, naive) and NK cells in mild and severe samples suggest an enhanced adaptive immune response as infection progresses, while the reduced abundance of Monocyte:CD14+ and Platelets in severe cases may reflect immune exhaustion or tissue damage." (PMID 40910395, 2025). "Sampling of blood and liver for analysis of CD4+ T cell immunity is also complicated because acute hepatitis C is often clinically silent and the onset of adaptive immunity occurs over a wide and unpredictable time frame of several weeks to months after infection." (PMID 40956619, 2025). "This single-round infection assay showed that the T/F virus had an advantage in infecting the CM CD4+ T cells over the SI strain (P < 0.0001, chi-squared test), while the SI strain had an advantage in infecting the EM CD4+ T cells (P < 0.0001, chi-squared test)." (PMID 41244297, 2025). "Initially increased CD4+ T cell responsiveness to Ag85B, which is involved in the synthesis of mycobacterial cell wall, decreases due to reduced expression of this Ag during chronic phase of infection, thereby restricting their capacity to control Mtb infections." (PMID 40414893, 2025). "The number of pulmonary CD4+ T cells did not change in the gene-deficient mice after infection." (PMID 41150440, 2025). "It remains possible that CD4+ T cells may become anergic or exhausted beyond the 2-week interval examined in this study, which could contribute to the inability to achieve sterilizing immunity in craniotomy infection." (PMID 39989461, 2025). "More critically, we also found that ROS levels in gated IgM+ B and CD4+ T lymphocytes increased significantly at 24 h post infection, suggesting that GCRV-II infection could potentially induce ROS accumulation in neighboring B and T lymphocytes within infected PBLs." (PMID 40733549, 2025). "Therefore, a CD4+ T-cell count of ≥500 cells/μL is considered a strong indicator of a satisfactory immunological recovery, since at this stage PLHIV and HIV-negative individuals are closely susceptible to similar types of infections." (PMID 40260259, 2025). "Interestingly, comparative analyses of the miRNA-seq profiles of GFP-positive cells with that of uninfected cells identified 17 upregulated and 20 downregulated miRNAs, indicating that the productive infection of CD4+ T cells also impacted the cellular miRNA expression profile." (PMID 39066239, 2024). "Additionally, we investigated the distribution of pathogens in patients with varying CD4+T lymphocyte counts and discovered that PLHIV with a CD4+T lymphocyte count of less than 50 cells/μL had significantly higher infection rates compared to those with a higher CD4+T lymphocyte count." (PMID 38774626, 2024). "In this work, we first identified human-relevant immunodominant SARS-CoV-2 CD8+ and CD4+ T cell epitopes in two different contexts: immunization with DNA-based vaccines encoding SARS-CoV-2 spike (S), membrane (M), or nucleocapsid (N) proteins; and infection with SARS-CoV-2." (PMID 38278784, 2024). "In addition, a breakthrough infection induced the formation of N-specific CD4+ T cells." (PMID 39640263, 2024). "However, consistent with the previous reports and our results of the comparable burden of Citrobacter rodentium in the early infection phase, the proportions of IL-22+ CD4+ T cells and IL-22+ ILC3 were maintained at an equal level in cLPs of water-restricted mice." (PMID 38799550, 2024). "However, future study is needed to determine whether Th1 subset CD4+ T cell response is responsible for the primary NMI infection-induced NMI-specific IgG2a response." (PMID 39469719, 2024).
infection (continued). "Looking forward, our research will integrate HIV new infection testing methodologies and epidemiological assessments to more precisely estimate the time of infection, thereby enhancing our understanding of the relationship between CD4+ T lymphocyte count and the timing of HIV acquisition." (PMID 38903589, 2024). "Likewise, changes in CD4+ T cell activation state has also been reported to modulate HIV entry and infection susceptibility with CD4+ T cells expressing the early activation marker CD69 being preferential targets of HIV infection relative to naïve cells in both blood and tissue." (PMID 39872519, 2024). "Additionally, they can transfer the virus to CD4+ T cells, further spreading the infection." (PMID 39496030, 2024). "NMI-infection induced a significant bodyweight loss in NMI-infected B cell deficient and T cell deficient mice at different times post-challenge but there was no significant bodyweight loss in PBS-infected WT, and NMI-infected WT, CD4+ T cell deficient and CD8+ T cell deficient mice." (PMID 39469719, 2024). "While HIV-1 cell-to-cell transfer between CD4+ T cells or from infected macrophages or dendritic cells to CD4+ T target cells have been largely explored, only a few studies investigating the mechanisms involved in cell-to-cell infection of macrophages have been reported so far." (PMID 38400063, 2024). "We used two independent methods to determine whether HIV was indeed mostly imported from other countries: first, a method based on the erosion of CD4 counts, and then molecular epidemiology using polymerase sequences to estimate the proportion of infections acquired abroad." (PMID 38921756, 2024). "CD4+T cells included several subsets, such as T helper 1 (Th1), Th2, Th9, and regulatory T cells (Tregs), CD4+T cells could indirectly involve in clearing infection via regulating the activity of macrophages, neutrophils, B cells, and other immune cells." (PMID 39135979, 2024). "In severe SFTS cases, the reduction in CD4 + and CD8 + T cell counts results in an insufficient number of active T cells to engage in cellular immune responses, thereby compromising cellular immune function and increasing the risk of infection from other pathogens." (PMID 38831352, 2024). "Moreover, it is believed that the production rate of IL-10 and both IFN-γ and TNF-α by human CD4+ T cells, and the regulated shift from one to the other during the course of infection, are crucial for the development of an appropriate but self-limiting immune response." (PMID 38787228, 2024). "However, the CD4+ cell subset was depleted compared to the Mtb single infection group." (PMID 39204027, 2024). "Interestingly, CD4+ and CD8+ CM T cells were among the most susceptible to infection (high %iHA+) of all nonphagocytic cells, while naive CD4+ and CD8+ T cells were the least susceptible (low %iHA+)." (PMID 38814732, 2024). "The host immune response effective to combat infection by bacteria of the Ehrlichia genus occurs through antigen presentation by conventional dendritic cells (CDC), followed by an acquired cellular immune response with activation of CD4+ cells in Th1 associated with humoral (Th2) responses." (PMID 39728964, 2024). "Ectopic STAT5 activation has recently been observed to alter the epigenome of CD4+ T cells and push their phenotype towards polyfunctionality, although such an alteration may present yet unidentified implications in the context of infection, perhaps playing a significant role in HIV pathogenesis." (PMID 38543785, 2024). "While it is possible that replication competency has a small impact on viral persistence before ART, the massive loss of both uninfected and infected CD4+ T cells during untreated infection suggests that virus production is not the primary factor causing depletion of CD4+ T cells before ART." (PMID 38422171, 2024). "Moreover, HIV-1-infected DCs can transfer the virus to CD4+ T cells via trans-infection." (PMID 38787201, 2024).
infection (continued). "However, in a natural HIV infection, the emergence of NAbs is delayed for 2–3 months; by then, most of the effector memory CD4+ T-cells (the main target cell of the virus) are already depleted, signifying that NAbs appear too late in natural infection to impact disease progression." (PMID 38932264, 2024). "Interestingly, a longitudinal study investigating the presence of SARS-CoV-2-specific CD4+ T cells at 6 to 15 months after infection calculated a t1/2 of 377 days, indicating a flattening of the contraction phase and suggesting the establishment of virus-specific long-term memory T cells." (PMID 39460293, 2024). "In addition, influenza virus-specific CD4+ T cells have been shown to have an essential role in protection against infection by indirectly supporting B-cell affinity maturation, eliciting CD8+ T-cell responses, and protecting in the absence of neutralizing antibodies in a mouse model." (PMID 39340038, 2024). "Thus, the importance of virus-specific CD4+ T cell-mediated clearance of infection within our model may be a result of its help to other immune cell populations, or through direct cytotoxic activity." (PMID 39575237, 2024). "Using a flow cytometry-based assay, the potential of 106 Nef clones (isolated from patients in early infection) to downregulate Ser5 in a CEM (acute lymphoblastic leukemia T-lymphoblast) -derived CD4+ T-cell line was evaluated in order to test their hypothesis." (PMID 39221250, 2024). "Importantly, this model assumes no causal relationship between multiple variant infection, higher log10 SpVL or the rate CD4+ T cell decline." (PMID 39471873, 2024). "If transcriptional rewiring triggered by CPSF6 recruitment to capsid cores enhances CD4+ T cell permissivity to infection, we would expect that mutations that prevent CPSF6 binding would decrease infectivity and that knock-out of CPSF6 would help rescue infection of those viruses." (PMID 39678349, 2024). "Importantly, the M-tropic viruses are able to enter and replicate in macrophages and dendritic cells but also in primary CD4+ T cells, whereas T cell-tropic viruses fail to enter into macrophages in vitro in cell-free infection assays, and can thus infect and replicate in CD4+ T cells only." (PMID 38400063, 2024). "Interleukin-17–producing CD4 T cells contribute to the control of Mycobacterium tuberculosis (Mtb) infection in humans; whether infection with human immunodeficiency virus (HIV) disproportionately affects distinct Th17-cell subsets that respond to Mtb is incompletely defined." (PMID 38698866, 2024). "Phenotypic analysis revealed that at all time-points post-vaccination, CD8+ and CD4+ MVA-specific T cells in COH04S1 vaccinees were predominantly T effector memory (TEM) cells, which have been associated with protection against peripheral infection with VACV21." (PMID 38366141, 2024). "This aligns with previously published data where no major differences for SARS-CoV-2 specific CD4+ or CD8+ T-cells were observed in different immunization sequences spanning from 3-course vaccination without infection to different timepoints/virus-variants plus vaccination combinations." (PMID 38049509, 2024). "Additionally, age at HIV diagnosis is used as a proxy for age at infection to estimate the duration from HIV infection to the date of the CD4 test, which may influence the accuracy of the CD4 depletion model." (PMID 38896338, 2024). "However, whether and how classical memory CD4+ T helper cells established during prior infections influence the magnitude and more importantly the nature of subsequent immune responses to heterologous challenges in vivo is still unclear." (PMID 38838013, 2024). "In addition, total RNA-sequencing data of PC-inoculated PCLS on day 3 and day 14 of culture showed that 99% of P. murina genes expressed during in vivo infection of CD4-depleted C57Bl/6 mice infected with P. murina for 2 weeks were maintained in the PCLS model." (PMID 38117035, 2024).